ABCA1 (ATP binding cassette subfamily A member 1)
Diseases named in the same sentence as ABCA1 in open-access papers (continued):
Sharing a sentence is not in itself a finding about the gene and the disease.
atherosclerosis (continued). "These and other data identified an important role of ABCG1 in the prevention of atherosclerosis, which allows us to consider ABCG1 along with ABCA1 as potential therapeutic targets for the prevention of atherosclerosis through the regulation of their expression, localization, and degradation." (PMID 36363640, 2022). "Interestingly, many traditional Chinese medicines are involved in ABCA1 regulation and demonstrate efficacy against atherosclerosis." (PMID 35743794, 2022). "Taken together, these results indicate that the correlation between ABCA1-miR-199a-5p could be exploited to control macrophage cholesterol efflux during the onset of atherosclerosis, where cholesterol alterations and hypoxia play a pathogenic role." (PMID 36407436, 2022). "KCNQ1OT1 promoted atherosclerosis development by modulating miR-452-3p/HDAC3/ABCA1 pathway." (PMID 36100884, 2022). "Overall, these results indicate that both pro-atherogenic stimuli, hypoxia and cholesterol overload in peritoneal macrophages, have similar opposite effects on miR-199a-5p and ABCA1 expression, suggesting a potential regulation of ABCA1 by miR-199a-5p during hypoxia and atherosclerosis." (PMID 36407436, 2022). "Thus, modulation of ABCA1 ubiquitination provides a novel therapeutic target for atherosclerosis treatment." (PMID 35743794, 2022). "Furthermore, among these genes, ABCA1 was downregulated via CRF signaling in the initial critical stage of atherosclerosis." (PMID 36676987, 2022). "As summarized in this review, we conclude that ABCA1 plays a role in a broad array of cardiovascular diseases, including dyslipidemia, atherosclerosis, ischemia/reperfusion, ischemic heart disease, myocardial infarction, and CHD, with different preventive effects." (PMID 35743794, 2022). "Thus, ABCA1 expression changes in tissues modified and damaged by atherosclerosis, such as plaques, macrophages, and mononuclear blood cells of patients with atherosclerosis." (PMID 34940525, 2021). "In general, the results of all these studies suggest that miR-33 contributes to the development of atherosclerosis in mammals by affecting many processes, including the reduction of ABCA1 expression, which decreases the RCT rate, at least under certain conditions." (PMID 34940525, 2021). "The authors suggested that the level of ABCA1 mRNA and the level of ABCA1 in macrophages may be essential factors in the development of atherosclerosis." (PMID 34940525, 2021). "Indeed, activation of LXRs reduces serum cholesterol and increases ABCA1-mediated cholesterol transport in humans and mouse/primate models of atherosclerosis, mainly by modulating lipid load in macrophages." (PMID 33841127, 2021). "As ABCA1 is critical in diseases such as atherosclerosis and Tangier disease, studying its functions in other models may provide new insight." (PMID 34200604, 2021). "Many studies have shown that ABCA1 plays an important inhibitory role in the formation of foam cells and that regulating the expression of ABCA1 at least partially inhibits the progression of atherosclerosis." (PMID 33767629, 2021). "Studies from our group and others have revealed that angiopoietin-1, pregnancy-associated plasma protein-A, and homocysteine inhibit ABCA1- and ABCG1-dependent cholesterol efflux from lipid-loaded macrophages and aggravate atherosclerosis in apoE−/− mice by downregulating LXRα expression." (PMID 33692340, 2021).
atherosclerosis (continued). "In rat atherosclerosis PCR array, Abca1, Bax, Bcl2, Bcl2a1, Cd44, Fabp3, Hbegf, Lypla1, Ptgs1, Selplg, Tgfb2, Tnc, and Vegfa had reverse trend between WT and MU groups, while the trends of Bcl2l1, Bid, Birc3, Cxcl1, Fas, Fn1, Itga2, Itga5, Lif, Nfkb1, Nr1h3, Ppard, and Sod1 were consistent." (PMID 34545275, 2021). "circDENND1B could sponge miR-17-5p and increase ATP binding cassette subfamily A member 1 (Abca1) expression, thus inhibiting atherosclerosis by promoting cholesterol efflux." (PMID 33996813, 2021). "On the contrary, mice deficient in ABCA1 and ABCG1 accelerate atherosclerosis." (PMID 34026849, 2021). "Moreover, overexpression of human ABCA1 in the liver and macrophages of C57Bl/6 mice reduced atherosclerosis." (PMID 34680102, 2021). "The assumptions about the participation of the transporter in the systemic mechanisms can be supported by observations in which a decrease in the level of mRNA ABCA1 in circulating white blood cells is determined in patients with atherosclerosis as compared to a control group." (PMID 34201488, 2021). "Moreover, overexpression of ABCA1 increased cholesterol efflux from macrophages and protected against atherosclerosis." (PMID 33951300, 2021). "Consistent with this explanation, we confirmed the markers related to dyslipidemia (e.g., PPARγ and leptin) in oleic and palmitic acid (OAPA) and lipopolysaccharide (LPS) treated-HUVECs for mimicking atherosclerosis of artery as well as ABCA1 and its target miRNAs." (PMID 34440128, 2021). "It should be noted that most miRNAs usually affect different mRNAs, so their effect on atherosclerosis development may not only be due to their influence on ABCA1." (PMID 34940525, 2021). "In this regard, the role of ABCA1 is well known in the pathogenesis of atherosclerosis." (PMID 34564491, 2021). "Moreover, ABCA1 expression is reduced in neointimal VSMCs compared with those isolated from the medial layer, more so in advanced relative to early atherosclerosis." (PMID 34686657, 2021). "Multifocal atherosclerosis is accompanied by decreased ABCA1 mRNA expression in EAT." (PMID 34837967, 2021). "The effect of such miRNAs on ABCA1 expression may be indirect but may still have importance for atherosclerosis development." (PMID 34940525, 2021). "The following aim was to determine whether remission of atherosclerosis by PBMT resulted from an up‐regulation of ABCA1 in vivo." (PMID 33951300, 2021). "Despite the primary focus on the potential of ABCA1 as a therapeutic target in atherosclerosis, its dual role in repressing inflammation while maintaining cholesterol homeostasis represents a promising therapeutic target for inflammatory lung diseases in the future." (PMID 32977800, 2020). "LXRβ activation is sufficient to reduce atherosclerosis and may contribute, together with LXRα, to the favorable upregulation of Abca1 and Abcg1 expression both in vivo and in vitro." (PMID 33233455, 2020). "Recent evidence suggested that dietary quercetin may be effective in lowering the risk of atherosclerosis by upregulating PPARγ, LXR-α, and ABCA1 and downregulating CD36 in the liver of apoE-/- mice fed HFD." (PMID 33261070, 2020). "In this review, we focus on the role of ANXA1 in atheroprogression and its novel interaction with ABCA1, which may be useful for providing basic knowledge for the development of novel therapeutic targets for atherosclerosis and cardiovascular disease." (PMID 32894039, 2020). "Decreased expression or localization of ABCA1 on the cell membrane may lead to cholesterol accumulation in macrophages and aggravate atherosclerosis." (PMID 32002588, 2020). "Thus, prevention of ABCA1-mediated cholesterol efflux is a critical mechanism by which kcnq1ot1 facilitates lipid accumulation and aggravates atherosclerosis." (PMID 33293505, 2020). "Furthermore, the ABCA1 level in SMCs in advanced atherosclerosis was decreased compared to early atherosclerosis; however, no changes in macrophages were observed." (PMID 33240650, 2020).
atherosclerosis (continued). "Although the data on the role of ABCA1 or cholesterol efflux in lymphocytes are scarce, the impairment of cholesterol efflux has been shown to stimulate the proliferation of CD4+ T lymphocytes, which are implicated in the development of atherosclerosis." (PMID 33658980, 2020). "PETIC may have a protective effect on obesity and atherosclerosis by regulating the expression of PPARγ, LXRα, ABCA1, SR-A1, CD36, and NF-κB." (PMID 33261070, 2020). "The second reported that anti-ApoA-1 IgG levels were inversely associated with PD- and positively associated with ABCA1-CEC in healthy obese subjects, with the capacity, to enhance ABCA1-CEC in vitro while repressing PD-CEC, leading to foam cell formation, the hallmark of atherosclerosis." (PMID 31766415, 2019). "Cav-treated macrophage-derived exosomes considerably promote cholesterol efflux as well as enhance ABCA1 expression, suggesting that macrophage-derived exosomes are capable of transmitting signals that participate in the protective effects of Cav in atherosclerosis." (PMID 31635197, 2019). "Cav halts atherosclerosis by enhancing cholesterol efflux and increasing ABCA1 expression in macrophages and in exosomes, possibly through NF-κB and Akt signaling, which provides mechanistic insights regarding the beneficial effects of Cav on atherosclerotic cardiovascular disease." (PMID 31635197, 2019). "Therefore, our present work was the first to reveal that enhancing HMGB1/TLR4 signaling induced by CUMS declined the expression of ABCA1 in aorta, leading to the development of atherosclerosis as confirmed by aortic sinus Oil Red O staining." (PMID 30881312, 2019). "This demonstrates that low ratio of n-6 to n-3 inhibits the formation of the foam cells as the quantity of cholesterol uptake via CD36 and biosynthesis via ACAT1 is less than the cholesterol efflux via ABCA1, which co-regulate to inhibit the development of the atherosclerosis." (PMID 29801502, 2018). "Thus, promoting the process of reverse cholesterol transport (RCT) by upregulating mainly ABCA1 remains one of the potential targets for the development of new therapeutic agents against atherosclerosis." (PMID 29751497, 2018). "ATP-binding cassette transporter A1 (ABCA1) is a key modulator of macrophage cholesterol efflux and protects against cholesterol accumulation and atherosclerosis, and knockout of Abca1 gene in macrophages promoted pro-inflammatory cytokines expression and activation of NF-κB." (PMID 30314997, 2018). "Importantly, a direct relation between ABCA1-mediated cellular cholesterol efflux and arterial-wall thickness exists that suggests the inhibition of atherosclerosis progression by efflux increase before the manifestation of symptomatic cardiovascular disease." (PMID 30174957, 2018). "ABCA1 is a key membrane ChE transporter, which is considered to counteract development of atherosclerosis by promoting cholesterol export from macrophages, overall contributing to reverse cholesterol transport (RCT), a process that eliminates cholesterol from the body." (PMID 30038271, 2018). "Recent results have demonstrated that paeonol could activate the liver X receptor α (LXRα)/ABCA1 pathway to accelerate ox-LDL outflow in macrophages, accompanied by reduction of foam cell formation and pathogenic changes of atherosclerosis." (PMID 30524649, 2018). "Double-knockout (ABCA1−/−/ABCG1−/−)mice displayed accelerated atherosclerosis development and observed massive foam cell formation in the myocardium, lung, liver, Peyer’s patches, lymph nodes, and spleen, and increased secretion of inflammatory cytokines and chemokines." (PMID 29113088, 2017). "Significantly, transplantation of bone marrow cells with genetic knockout of Abca1 and Abcg1 into mouse models prone to developing atherosclerosis resulted in accelerated atherosclerosis, underscoring an athero-protective role for these transporters in myeloid cells." (PMID 29069761, 2017).
atherosclerosis (continued). "Generation of dysfunctional HDL through MPO-mediated oxidative damage to apolipoprotein A-1 (ApoA1), the major HDL protein, is associated with inability of HDL to remove cellular cholesterol by the ATP-binding cassette transporter A1 (ABCA1) pathway in humans with atherosclerosis." (PMID 29333213, 2017). "This implies that enhanced ABCA1 activity can protect against atherosclerosis in vivo." (PMID 27664032, 2017). "Notably, ABCA1 plays a critical role in exporting cholesterol from macrophages to protect against the development of atherosclerosis." (PMID 29254143, 2017). "Mice deficient in the p50 subunit of NFκB on a high-cholesterol diet are protected from IH-induced ABCA1 inhibition and accelerated atherosclerosis, suggesting that ABCA1 and ABCG1 inhibition in IH may be mediated by NFκB activation." (PMID 26738794, 2016). "On the other hand, overexpression of ABCA1 retards signs of atherosclerosis in mice." (PMID 26317415, 2015). "Thus, PRMT2 represents a glucose-sensitive factor that plays a role in LXR-mediated ABCA1-dependent cholesterol efflux and lends insight to the presence of increased atherosclerosis in diabetic patients." (PMID 26288135, 2015). "Also, it has been shown that overexpression of ABCA1 gene can confer protection against atherosclerosis." (PMID 26788366, 2015). "ABCA1 overexpression has been shown to protect C57BL/6 mice from diet-induced atherosclerosis." (PMID 25604880, 2015). "As the rate of release of FC from the lysosome is a regulator of ABCA1 expression, lysosomal dysfunction in atherosclerosis may also lead to decreased expression of ABCA1 in artery wall cells." (PMID 25699256, 2015). "The function of ABCA1 in the development of atherosclerosis has also been confirmed in animals." (PMID 25958224, 2015). "Thus, future studies directed at elucidating PRMT2 substrates, regulation and in vivo function in macrophages would be crucial for understanding the role PRMT2 plays in LXR-mediated regulation of Abca1 in diabetes and atherosclerosis." (PMID 26288135, 2015). "Moreover, in studies in animal models of hypercholesterolemia and atherosclerosis, researchers have reported that miR-33a suppresses the expression of ABCA1 and lowers HDL levels, whereas inhibition of miR-33 increases ABCA1 and HDL levels." (PMID 25880168, 2015). "ABCA1 is a key player in cholesterol efflux frommacrophages to lipid‐free apo‐A1 in a process known as reversecholesterol transport, a role that is important in atherosclerosis." (PMID 26650446, 2015). "The role of the cholesterol transporters ABCA1, ABCG1 and SR-BI in macrophage cholesterol efflux has been extensively studied, and it has been shown that impaired cellular cholesterol efflux is associated with atherosclerosis in humans." (PMID 25181357, 2014). "ABCA1 is known to play a key role in cholesterol homeostasis and anti-atherosclerosis." (PMID 24733347, 2014). "Furthermore, macrophage-specific overexpression of ABCA1 inhibits the progression of atherosclerosis, whereas macrophage-specific inactivation of ABCA1 increased foam cell formation and atherosclerosis." (PMID 24324556, 2013). "Moreover, animal studies show that in transgenic mice disruption of ABCA1 gene induces atherosclerosis, in which it was shown that cholesterol crystals activate the inflammasome." (PMID 24312444, 2013). "Taken together, these results reveal a novel mechanism for the BA-mediated ABCA1 expression, which may provide new insights for developing strategies for modulating vascular inflammation and atherosclerosis." (PMID 24086374, 2013). "The identification of ATP-binding cassette transporter A1 (ABCA1) as a rate-limiting factor in HDL-C biogenesis suggested that increased ABCA1 activity could inhibit atherosclerosis." (PMID 23316322, 2012). "Conversely, mice with macrophage overexpression of ABCA1 have decreased atherosclerosis." (PMID 22984960, 2012).
atherosclerosis (continued). "Consequently, impaired ABCA1 activity is associated with low plasma HDL, which is linked to Tangier disease, familial HDL deficiency, and accelerated atherosclerosis." (PMID 22919365, 2012). "The purpose of the present study was to analyze whether the ABCA1/R230C variant is associated with premature CAD and subclinical atherosclerosis in a case-control association study: GEA (Genetics of Atherosclerotic Disease)." (PMID 23152888, 2012). "The likely beneficial effects of the higher expression of PPARA seen here for female liver include increases in HDL levels, decreases in triglycerides via increased beta-oxidation, induction of ABCA1, increases in insulin sensitivity, and protection from atherosclerosis." (PMID 21858147, 2011). "We found that mRNA expressions of ABCA1 and SR-BI in hepatocytes were significantly lower in atherosclerosis group than in control group, but they were significantly higher in probucol group than in atherosclerosis group." (PMID 22078494, 2011). "We found that ASA increased the expression of SR-BI and ABCA1, so reducing the cholesterol levels in foam cells and potentially slowing down the progression of atherosclerosis, which is in agreement with the observations made by Cyrus T in the low LDL receptor-deficient mice." (PMID 20137092, 2010). "Considering the potential connections among MMP-9, SR-BI, ABCA1 and NF-κB in related to inflammation and atherosclerosis, and the regulatory roles played by ASA in these mechanisms, we investigated the effects of ASA on the expressions of these molecules using highly relevant human macrophages." (PMID 20137092, 2010). "CSN3 can inhibit ABCA1 degradation by binding to it, while substances such as cadmium, AGEs, and APOE4 differentially regulate ABCA1 stability by affecting ubiquitination or lysosomal function, thereby being associated with pathological processes such as atherosclerosis and Alzheimer’s disease (AD)." (PMID 41303341, 2025). "Thus, ABCA1 plays an important role in reducing atherosclerosis development." (PMID 40176913, 2025). "Listerin catalyzed K63-linked polyubiquitination of ABCA1 at lysine sites K1884 and K1957 and inhibited its degradation through the ESCRT lysosome pathway, which further promoted the cholesterol efflux of macrophages, inhibited foam cell formation, and ameliorated atherosclerosis development." (PMID 40526435, 2025). "Both the expression of ATP-binding cassette transporter A1 (ABCA1) and its binding to apolipoprotein A-I (ApoA1) of high-density lipoproteins (HDLs) are reduced in human SMCs, with this impairment appearing to be more pronounced in the advanced stages of atherosclerosis." (PMID 38952543, 2024). "Notably, Qing-Xue-Xiao-Zhi formula (QXXZ, 清血消脂方), Si-Ni decoction (四逆汤), Qi-Shen-Yi-Qi Pill (芪参益气丸), and Yin-Xing-Tong-Mai decoction (银杏通脉汤) have been demonstrated to attenuate hyperlipidemia and atherosclerosis by facilitating RCT through upregulation of PPARγ–LXRα–ABCA1/ABCG1 signaling pathways." (PMID 38699583, 2024). "Therefore, inhibiting miR-33a-5p within inflamed endothelium may prevent and treat atherosclerosis by enhancing apoAI-mediated cholesterol efflux by upregulating ABCA1." (PMID 37489440, 2023). "Since liver X receptor (LXR), a nuclear receptor, regulates the expression of genes involved in cholesterol efflux, including Abca1, Abcg1, and Apoe, in atherosclerosis and aged mice, we examined whether the LXR agonist, GW3965, promotes cholesterol efflux from spinal cord lesions." (PMID 37223476, 2023). "Moreover, the ability of TFEB to mitigate the progression of atherosclerosis is partly due to its induction of the cholesterol efflux regulatory protein, ATP‐binding cassette transporter (ABCA1), and concomitant downregulation of the class B scavenger receptor, CD36." (PMID 37728021, 2023). "Many studies have shown that ABCA1 may play a dual role in the development of atherosclerosis." (PMID 35743794, 2022).